AZGP1P2 (AZGP1 pseudogene 2)
Gene: Transcribed unprocessed pseudogene on chromosome 7 (101,287,482 to 101,289,771, reverse strand). Ensembl gene ENSG00000214252.
Diseases named in the same sentence as AZGP1P2 in open-access papers:
AZGP1P2 is named in the same sentence as 3 diseases in open-access papers, as found by Europe PMC text mining. Sharing a sentence is not in itself a finding about the gene and the disease. The quoted sentences say what the papers report.
prostate carcinoma (2 papers, 2023 to 2026). A carcinoma that arises from epithelial cells of the prostate gland. "AZGP1P2 overexpression enhances the sensitivity of castration-resistant prostate cancer cells to docetaxel, reduces migration, increases apoptosis, and reduces prostate CSC markers, including KLF4 and SOX2, in castration-resistant prostate cancer cells." (PMID 41431719, 2026). "In the current study, we have demonstrated, for the first time, the function and mechanisms of AZGP1P2 in controlling the treatment resistance of docetaxel in CRPC by regulating the stemness of prostate cancer stem cells (PCSCs)." (PMID 37854295, 2023).
tumor (2 papers, 2023 to 2024). "We found that AZGP1P2 was downregulated in PCa and stem-like tumor cell Mechanistically, AZGP1P2 combines with RBM15 and ubiquitin-like modifier activating enzyme 1, promoting the ubiquitination and degradation of the former at the protein level." (PMID 38798700, 2024). "In this study, we have found that AZGP1P2, acting as a tumor suppressor, was downregulated in CRPC cells, and its low expression level indicated the poor prognosis of PCa." (PMID 37854295, 2023). "Collectively, these results imply that AZGP1P2 mediates the stemness and apoptosis of PCSCs and promotes docetaxel therapeutic effect by suppressing tumor growth and metastasis via UBA1/RBM15-mediated TPM1 mRNA decay in CRPC." (PMID 37854295, 2023). "For the in vivo assay, the tumor volumes were drastically diminished by RBM15 silencing in CRPC cells, and the decreases were restored by AZGP1P2 knockdown." (PMID 37854295, 2023). "Furthermore, in vivo assay with the subcutaneous xenograft mouse model showed that AZGP1P2 overexpression decreased the tumor growth of CRPC cells treated with docetaxel, which illustrates that AZGP1P2 plays an important role in improving the sensitivity of docetaxel chemotherapy in CRPC cells." (PMID 37854295, 2023).
AZGP1P2 also shares sentences with these, for which no sentence is quoted: cancer (1 paper).